BRCA1 (BRCA1 DNA repair associated)
Diseases named in the same sentence as BRCA1 in open-access papers (continued):
Sharing a sentence is not in itself a finding about the gene and the disease.
cancer (continued). "It is noteworthy that BRCA1 and SMC3 are present at the plasma membrane and basement membrane respectively and involved in the regulation of cell spreading and motility in cancer cells." (PMID 23717600, 2013). "Endogenous BRCA1 defective cancer cells (MDA-MB-436, HCC1937) exhibited higher sensitivity to cucurbitacin B than the wt-BRCA1 expressed cells (MCF-7, MDA-MB-231)." (PMID 23393598, 2013). "We will also describe a recently identified and under-investigated role for BRCA1 in the regulation of telomeres and the implications of this role in the DDR and cancer suppression." (PMID 23802008, 2013). "A significantly higher MVD was observed in BRCA1-2 carrier than in BRCAX, and in sporadic cancer tissues, (p = 0.002 and p = 0.0001 respectively)." (PMID 23326384, 2013). "In our study a higher and more intensive cytoplasmic VEGF expression was evident both in tumor cells of BRCA1-2 carriers and of BRCAX cancers compared to tumor cells of sporadic cancers." (PMID 23326384, 2013). "Among the genes whose translational level is significantly changed in response to BRCA1 depletion in MCF7 cells, we have selected those that were shown to play a role in cancer and we discuss below results concerning 5 of them." (PMID 23805307, 2013). "There was substantial variation in number and pattern of indel, however, with more and larger indels observed in BRCA1 and BRCA2 mutant cancers." (PMID 22608084, 2012). "BRCA1 and BRCA2 cancers are particularly responsive to some DNA damaging agents and inhibitors of DNA repair, notably PARP inhibitors." (PMID 22608084, 2012). "Mutational patterns, which are probably more closely related to the underlying biological defect, therefore appear to report similarities in disease pathogenesis between BRCA1 and BRCA2 mutant cancers better than cellular phenotype." (PMID 22608084, 2012). "A relationship has been suggested between HMGB1 and cancer based on findings that HMGB1 regulates the transcription of many cancer genes, such as E-selectin, TNF-α, insulin receptor, and BRCA1." (PMID 22496788, 2012). "These similarities in mutational signatures contrast strikingly with differences in histology and gene expression profiles between BRCA1 and BRCA2 mutant cancers." (PMID 22608084, 2012). "We recently showed that BRCA1-IRIS overexpression promotes expression of AKT1, AKT2, p-AKT and survivin in human ovarian normal and cancer cell lines." (PMID 22511931, 2012). "A clinically relevant example of how the decreased LD lengths can affect impact SNP-tagging is observed in the BRCA1 and JAK2 cancer genes." (PMID 22811759, 2012). "Rearranged genes showed to be highly connected to well-known altered genes in cancer such as AR, RB1, MYC, and BRCA1." (PMID 22811706, 2012). "Several studies support resveratrol inducing a sustained DNA damage response via BRCA1 and activation of the ATM/ATR-Chk1/2-Cdc25C pathway in cancer cells." (PMID 22247744, 2011). "Although BRCA1- and BRCA2-related cancers demonstrate somewhat distinct picture of genetic abnormalities, they both have increased number of gross chromosomal aberrations and therefore higher tumor grade." (PMID 21819606, 2011). "We further established an inverse significant correlation between BRCA1 expression levels and CD44+ cancer cell phenotype (p=0.02)." (PMID 23508738, 2011). "So, it seems that haploinsufficiency for BRCA1 or BRCA2 in heterozygous women contributes to progressive telomere shortening at a somatic and germline level, affecting the age of cancer onset in successive generations." (PMID 21829373, 2011).
cancer (continued). "A number of studies have illustrated that BRCA1/2 pre-cancerous cells are very sensitive to PARP inhibition, whilst cancer cells exhibit different responses to PARP inhibition under a variety of different conditions." (PMID 20961453, 2010). "Aberrant DNA methylation of CDKN2A has been observed in a wide range of common cancer types, while VHL and BRCA1 are silenced by methylation in a significant proportion of kidney and breast and ovarian cancers, respectively." (PMID 19285540, 2009). "In paired specimens, BRCA1 protein expression increased in 13/21 (62%) and BRCA2 protein expression increased in 15/21 (71%) of recurrent carcinomas with low or intermediate protein in the paired primary." (PMID 19602291, 2009). "CK-14 was detected in 35% of 161 ER/HER2-negative cancers and 37% of the ER/HER2-negative and BRCA1-positive group." (PMID 18275599, 2008). "This is particularly true for the BRCA1 and BRCA2 groups, which suggested that the incremental cost per detected cancer with CE MRI (combined with mammography or with CE MRI alone) is £11 800 and £15 300 respectively when compared to mammography alone." (PMID 17016484, 2006). "For the BRCA1 (BRCA2) group, the number of cancers detected was three out of 13 (6 out of 12), 12 out of 13 (7 out of 12) and 12 out of 13 (11 out of 12) by mammography, CE MRI and CE MRI and mammography combined respectively." (PMID 17016484, 2006). "Various proteins that associate with centrosomes such as pericentrin, STK15/BTAK/Aurora-A kinase, ATR, BRCA1, BRCA2, have been shown to influence centrosome duplication in human cancer." (PMID 17081288, 2006). "In this study, the familial non-BRCA1/2 cancers were diagnosed at a marginally younger age than those among unselected cases, and were more often of lower grade than the control cancers or BRCA1 and BRCA2 cancers." (PMID 15642173, 2005). "We therefore selected 3 cell lines encoding BRCA1 (UWB1.89 and HCC1937) or ATM (H1395) mutations, with non-mutated SKOV3, MCF-7 and A549 cell lines as cancer-type matched controls." (PMID 39994444, 2025). "BRCA1/2 gene mutations predict PARPi sensitivity; however, the majority of cancer patients carrying normal BRCA1/2 genes are not eligible for PARP inhibitors." (PMID 40299557, 2025). "Identification of the BRCA1 and BRCA2 genes was an enormous step in cancer research." (PMID 41514592, 2025). "Genetic testing was negative for BRCA1/2, CHEK2, and PALB2 mutations, though familial cancer history suggested a possible hereditary syndrome (FCC suspicion)." (PMID 40926949, 2025). "Our findings highlight the strength of our mutational signature–based classifiers CSI-HRD for detecting HRD across diverse cancer types, even in the absence of canonical BRCA1/2 alterations." (PMID 41279139, 2025). "Although OFD1 is not directly involved in DNA damage repair, it regulates BRCA1 transcription in a stress-inducible manner, making it a promising target for cancer therapy." (PMID 40764600, 2025). "In order to reduce heterogeneity among the patients with cancer, the analysis was conducted after excluding data for one patient who did not meet the BRCA1/2 genetic testing criteria." (PMID 40900191, 2025).
cancer (continued). "The vast majority of BRCA1 mutant cancers are ER-alpha negative and ER-PR-HER2 negative (triple-negative), appearing to develop independently of estrogen regulation." (PMID 41514592, 2025). "It was recently shown that a substantial percentage of BRCA1 and BRCA2 mutated cancers do not lose their wild type allele through locus-specific LOH43." (PMID 41034557, 2025). "This fork remodeling represents a critical mechanism of acquired PARP inhibitor resistance in BRCA1 mutant cancers, playing a role irrespective of HR restoration." (PMID 41155174, 2025). "Because YAP/TAZ-TEAD transcriptional activity governs RAD51 expression in cancer cells, whether SOX5 inhibition regulates YAP and the HR repair genes, BRCA1 and RAD51, in olaparib-resistant cells was investigated." (PMID 40274769, 2025). "However, in other cancers, oHRR biallelic alterations exhibited significantly higher HRD scores than BRCA1/2 biallelic alterations (P<0.001) and oHRR monoallelic alterations (P<0.001), but comparable to wild-type groups (P>0.05)." (PMID 40420266, 2025). "Among them, 11 BRCA1 and BRCA2 PV carriers had a history of cancer." (PMID 39825003, 2025). "More precisely, cancer cells lacking the repair proteins BRCA1 and BRCA2 rely more heavily on PARP to repair their damaged DNA." (PMID 41347092, 2025). "Furthermore, curcumin has been shown to modulate the expression of genes involved in DNA repair, such as BRCA1 and DNMT1, ultimately leading to apoptosis in various cancer cell lines." (PMID 40725041, 2025). "CBC was the commonest cancer in all groups (BRCA1 PV carriers: 66 events, BRCA2 PV carriers: 43 events, noncarriers: 237 events)." (PMID 39475295, 2025). "Overall, 38.1% of cancer samples with BRCA1/2 mutations, 10.9% of tumors with alterations in HRR genes other than BRCA1/2, and 4.3% of cancer samples without HRR gene mutations harbored an elevated GIS." (PMID 40278800, 2025). "Mutations in BRCA1, BRCA2, and non-BRCA cancer susceptibility genes accounted for 34.9% (n = 213), 31.6% (n = 193), and 35.1% (n = 214), respectively." (PMID 38355628, 2024). "Delaying surgery by 5 years for BRCA1 (RRM at age 35 years; RRSO at age 40 years) and BRCA2 (RRM at age 40 years; RRSO at age 45 years) was still cost-effective but with reduced QALYs and NMB and fewer cancers prevented." (PMID 38334999, 2024). "Cells devoid of functional BRCA1 or BRCA2 proteins may undergo uncontrolled proliferation, leading to the development of cancer." (PMID 38809921, 2024). "We did not have information about the history of BRCA1/2 tests as the cancer registry does not have access to the results of genetic testing." (PMID 39124739, 2024). "Interestingly, E7820-mediated double-strand breaks in DNA were increased in tumors with BRCA2 dysfunction, and knockdown of BRCA1/2 transcripts or knockout of ATM, ATR, or BAP1 sensitized cancer cells to E7820." (PMID 38789724, 2024). "Three patients with known germline mutations in either BRCA1/2 had tumour profiling performed on the AmpliSeq Cancer Hotspot V2 test panel, which did not include BRCA1/2, and thus, somatic BRCA alterations were not identified." (PMID 38812774, 2024). "As for the rest of the non-TNBC, the so-called HER2-enriched and the luminal cancers having an ER expression > 10%, BRCA1 epimutations were observed in about 2% only." (PMID 40225940, 2024).
cancer (continued). "Investigating the interplay and molecular mechanism between BRCA1/BRCA2 and autophagy could provide further insights into cancer biology and therapeutic strategies promoting precision medicine." (PMID 39199310, 2024). "The BRCA1-53BP1 pair determines the pathway choice between HR and NHEJ, disturbance of which leads to mutagenic processes and rapid evolution of the cancer genome." (PMID 38263342, 2024). "Age at RRSO and time after RRSO negatively predicted psychological symptoms in BRCA1 carriers, women without a history of cancer, those who were premenopausal at the time of RRSO, current non-smokers, and those who exercised for more than 4 days." (PMID 39201170, 2024). "The discovery of the BRCA1 and BRCA2 genes proved to be a breakthrough in cancer research." (PMID 39329990, 2024). "Furthermore, AM-1882 is active in a subset of cancer cell lines with CCNE1, BRCA1 and RB1 gene alterations and can enhance apoptosis when combined with PARP inhibition." (PMID 38151625, 2024). "Despite the observed improvement in outcomes from PARP inhibitors, up to 40% of patients with BRCA1/2-mutant cancers either do not respond initially to PARP inhibition or develop resistance to it8." (PMID 39730675, 2024). "According to this concept, restraining PARP1 could be a latent therapeutic schedule for the therapy of cancers with defects in precise DNA repair genes, such as XRCC2, MRE11, and BRCA1/2." (PMID 38907095, 2024). "Dose–response experiments were performed using the BRCA1 and BRCA2 wild-type breast (MDA-MB-231 and MCF-7) and ovarian (HEY-T30 and SKOV-3) cancer cell lines to determine the differences in their drug sensitivity and the concentrations appropriate for the drug combination experiments." (PMID 39273190, 2024). "An analysis using an expanded set of cancer-related genes (COSMIC Cancer Gene Census), produced similar results with no other recurrently mutated gene significantly enriched in BRCA1/BRCA2 mutant cancers." (PMID 39198848, 2024). "Notably, BRCA1 and MGMT mRNA levels were greater in the WBC RNA of the BC patients and cancer-free methylation carriers than in that of the OC patients." (PMID 38542081, 2024). "In addition, somatic alterations in BRCA1/2 and other HR-related genes such as ATM or RAD51 are prevalent among several cancer types including ovarian, breast, pancreas, and prostate, among others." (PMID 39544936, 2024). "Additionally, we assessed BRCA1 and BRCA2 expression in normal esophageal cells and EC cells and found that HMGA1, BRCA1, and BRCA2 were highly expressed in cancer cells." (PMID 39690136, 2024). "Women with prevalent BC and carriers of BRCA1 and BRCA2 mutations did not have on-time annual screenings any more than women low cancer risk." (PMID 38564263, 2024). "The relevance of the BRCA1/BARD1 ubiquitin E3 activity for HR in terms of DNA DSB repair and treatment resistance remains contradictory in current literature, due to the use of different approaches involving diverse cancer cell lines and models." (PMID 38769345, 2024). "Similarly, for INMON, FOXO3 and IRF5 were common TFs in healthy and early-stage tissues (e.g., BRCA1-mut); specifically, PRDM4 was the TF in precancer stages (e.g., Goiters and HT) while ATF2 and RUNX1 were enriched in cancers (e.g., ESCC and IDC)." (PMID 38645221, 2024). "For example, pathogenic germline variants in BRCA1 and BRCA2 genes, which play a fundamental role in DNA repair, confer a greatly increased risk of some, but not all, types of cancer." (PMID 39625477, 2024).
cancer (continued). "Although cells with WT and functional BRCA1/BRCA2 activate the canonical Wnt/β-catenin–dependent signaling pathway upon Wnt3A treatment, cancer cells that lose BRCA1 function activate the noncanonical β-catenin–independent pathway instead." (PMID 39028933, 2024). "In particular, two major homologous recombination repair (HRR) genes, BRCA1 and BRCA2, become nonfunctional in cancer through loss of function (LOF) mutations or hypermutations in the promoter region." (PMID 37298484, 2023). "In both BRCA1 and BRCA2 mutated cohorts, the mean age at cancer diagnosis is not statistically different in cases with ALDH2 AA genotype than those with the GG or GA." (PMID 36345163, 2023). "Oxidative stress at replication forks is a common problem in many malignancies, not just BRCA1-mutant cancers, as cancer cell metabolism generates oxygen free radicals to a higher extent than normal cells." (PMID 36683914, 2023). "Moreover, Vohhodina and colleagues showed that BRCA1 directly binds TERRA RNA and also suppresses its expression in the ALT+ cancer cells." (PMID 37035242, 2023). "Although the small, heterogeneous population of patients with BRCA1-altered cancers did not allow formal statistical analysis, CBR in this population was approximately 48%." (PMID 37277454, 2023). "The transient formation of R-loops in ALT cancer cells provokes replication stress, but it also signals an early stage of DNA repair by recruiting RAD51, BRCA1, and other repair factors and initiating HR-mediated telomere synthesis induced by DNA strand breaks." (PMID 37046839, 2023). "By surveying the presence of these signatures across human cancers, it is clear that many tumors exhibit HRD-associated signatures even in the absence of BRCA1/2 mutations." (PMID 36964191, 2023). "In addition to BRCA1, highly expressed E3 ligase in specific cancer cells is likely to cross-connect DDR to cancer metabolism." (PMID 37176148, 2023). "Significant disturbances in the mechanism of DSB DNA repair in the absence of fully functional BRCA1 or BRCA2 make cancer cells particularly sensitive to PARP inhibitors, especially in the case of LOH." (PMID 36902416, 2023). "Independently from their role in canonical homologous recombination, BRCA1 and BRCA2 are required for the protection of newly replicated DNA from promiscuous nuclease activities, a function with important implications for both cancer biology and therapy." (PMID 37364916, 2023). "In addition to BRCA1 and BRCA2, many other HRR mediators (ATM, BRIP1, CHEK2, NBS1 or RAD51C) are frequently defective in cancer." (PMID 37298484, 2023). "In this sense, FBXO9 might mimic BRCA1 and BRCA2, the well-established cancer suppressors for OV that maintain genomic stability via facilitating DNA damage repair and are dysfunctional in a large portion of OV patients." (PMID 38136595, 2023). "For example, Hereditary Breast and Ovarian Cancer (HBOC) syndrome caused primarily by variants in BRCA1/2 which have overlapping functions with BLM, is associated with increased cancer risk without syndromic features." (PMID 37594403, 2023). "By extending the investigative timeline and scrutinizing the potential impact on cancer incidence, we investigate a fundamental hypothesis: Could BPA amplify the tissue-specific tumorigenic potential of BRCA1, catalyzing cancer initiation and progression?" (PMID 37762577, 2023). "Cancer cells lacking functional BRCA1 or BRCA2, critical players in homologous recombination repair, are more sensitive to PARP inhibition." (PMID 36978917, 2023). "Heterozygous carriers of FANCI c.1813C>T were identified more commonly in OC families negative for BRCA1 and BRCA2 pathogenic variants compared to FC cancer-free controls." (PMID 36833203, 2023).